TGFB1 (transforming growth factor beta 1)
Diseases named in the same sentence as TGFB1 in open-access papers (continued):
Sharing a sentence is not in itself a finding about the gene and the disease.
chronic cervicitis (1 paper, 2024). Chronic inflammation of the cervix. "We used a set of patient-derived precancerous (n = 32) and noncancerous (chronic cervicitis; n = 10) tissue samples to investigate the gene expression of several OIS (LMNB1, CDKN2A, CDKN2B, and CDKN1A), and SASP (IL1A, CCL2, TGFB1, CXCL8, and MMP9) biomarkers using qRT-PCR." (PMID 39727946, 2024).
Coccidioides infection (1 paper, 2025). "In response to Coccidioides infection, Spp1+ macrophages express high levels of pro-inflammatory (Nos2, Tgfb1, Il1β, and Il6) and fibrotic/wound healing associated genes (Inhba, Spp1, Arg1, Pdgfb, and Fn1)." (PMID 40704794, 2025).
dental caries (1 paper, 2024). The decay of a tooth, in which it becomes softened, discolored, and/or porous. "There are seven key proteins involved in the action of curcumin on dental caries: MAPK1, BCL2, KRAS, CXCL8, TGFB1, MMP9, and IL1B, all of which spontaneously bind curcumin." (PMID 38920854, 2024).
dermopathy (1 paper, 2005). "The recent emergence of a newer skin pathology termed: neprogenic fibrosing dermopathy may appear co-morbidly with CPLX and recently it has been reported that transforming growth factor beta-1 (TGF beta-1) may to be related to both disorders." (PMID 15777477, 2005).
developmental disabilities (1 paper, 2019). "We and others have shown that plasma levels of TGFβ1 were reduced in ASD compared to TD controls and children with other developmental disabilities." (PMID 31252635, 2019).
gastroschisis (1 paper, 2018). Gastroschisis is marked by viscera protruding, without a covering sac, from the fetal abdomen on the right lateral base of the umbilicus. "One could also speculate that in the malformation called gastroschisis, where herniated gut fails to return to the abdominal cavity, the intestine would suffer overexposure to growth factors in the amniotic including TGFβ1." (PMID 28084682, 2018).
glucocorticoid resistance (1 paper, 2023). "The fluctuation of TGFβ1 and TGFBR2 allowed us us to speculate that such configuration may favor TNFα pro-inflammatory signaling to induce an acute form of glucocorticoid resistance (GCR)." (PMID 37301958, 2023).
glucosuria (1 paper, 2021). "The association of overexpressing tubular TGF-β1 with the development of albuminuria, polyuria, and glucosuria in DN may be due to the impairment of renal reabsorption as Tgfb1-hypermorphic Akita mice show decreased expression of megalin." (PMID 34360646, 2021).
Granular corneal dystrophy (1 paper, 2015). The presence of central, fine, whitish granular lesions in the stroma of the cornea. "The effective epigenetic regulation of histone H3K4me during the TGFβ1-mediated expression of TGFBIp and ECM genes in corneal fibroblasts could be used to create cornea-protective therapies for granular corneal dystrophy." (PMID 26553048, 2015).
Gynecomastia (1 paper, 2025). Abnormal development of large mammary glands in males resulting in breast enlargement. "Ten key genes associated with gynecomastia were identified, including IGF1, TGFB1 and AR, alongside 12 candidate drugs with promising binding affinities, such as yifenidone, conteltinib and vosilasarm." (PMID 40002676, 2025). "Our findings highlight the potential therapeutic relevance of targeting pathways involved in growth factor signaling (e.g., IGF1R and TGFB1), androgen receptor modulation and melanocortin signaling for managing gynecomastia." (PMID 40002676, 2025).
idiopathic nephrotic syndrome (1 paper, 2022). Nephrotic syndrome for which no cause has been identified. "TGFβ-1 seems to be directly upregulated by HMGB1-triggered routes, and there is supporting evidence of elevated urinary levels of TGFβ-1 in children with idiopathic nephrotic syndrome and in focal and segmental glomerulosclerosis (FSGS)." (PMID 36551967, 2022).
keratitis (1 paper, 2023). A corneal disease that is characterized by inflammation of the cornea. "Indeed, we found a strong upregulation of TGFB1 in both bacterial/fungal and viral human keratitis, indicating a potential application of TGF-beta inhibitors to reduce corneal scaring." (PMID 38274739, 2023).
lactic acidosis (1 paper, 2023). Metabolic acidosis characterized by the accumulation of lactate in the body. "Under the same experimental conditions (i.e., lactic acidosis or TGFβ1), the percentages of α-SMA-positive and COL1A1-positive cells/hpf were significantly increased compared to those under basal conditions." (PMID 36980280, 2023). "In contrast, we did not observe any significant variation in acADSC viability or proliferation when grown in basal conditions, lactic acidosis, or in the presence of TGFβ1." (PMID 36980280, 2023). "In fact, acADSCs treated with TGFβ1, compared to those grown under basal conditions, displayed a mesenchymal-like, elongated shape—even further marked compared to lactic acidosis—accompanied by a considerable decrease in intracytoplasmic lipid droplets." (PMID 36980280, 2023). "Briefly, we observed a significant decrease in FABP4, adiponectin, and perilipin-1 protein expression both in acADSCs grown under lactic acidosis and in those treated with TGFβ1 compared to basal conditions." (PMID 36980280, 2023). "The number of cells containing cytoplasmic lipid droplets was significantly decreased in both acADSCs cultured under lactic acidosis and those stimulated with TGFβ1 compared to cultures maintained in basal (pH 7.4) medium." (PMID 36980280, 2023). "In particular, the percentages of perilipin-1-positive and adiponectin-positive cells/hpf were approximately three times decreased in acADSCs grown under lactic acidosis, as well as following TGFβ1 treatment, compared to those maintained in basal (pH 7.4) medium." (PMID 36980280, 2023). "Besides viability, cell proliferation evaluated by MTT assay was also not altered, despite a slight but non-significant decreasing tendency observed in acADSCs subjected to lactic acidosis or TGFβ1 treatment." (PMID 36980280, 2023). "The acADSC treatment with 10 ng/mL TGFβ1 was able to stimulate IL1B and IL6 gene expression at a similar level to lactic acidosis." (PMID 36980280, 2023).
lattice corneal dystrophy type I (1 paper, 2023). Type I lattice corneal dystrophy (LCDI) is a frequent form of stromal corneal dystrophy characterized by a network of delicate interdigitating branching filamentous opacities within the cornea with progressive visual impairment and no systemic manifestations. "Finally, TGFB1 has been determined to cause lattice corneal dystrophy type 1, Avellino, and Reis–Bucklers." (PMID 36981008, 2023).
ligament diseases (1 paper, 2021). "It has been shown in bone and ligament diseases that ASPN inhibits the TGFβ ligand (TGFB1)." (PMID 34379688, 2021).
lymph node disease (1 paper, 2017). "High TGFβ1 expression remained statistically significant and has the greatest association with survival except for family history of PDAC and positive lymph node disease." (PMID 27895310, 2017).
lymphoproliferative disorders (1 paper, 2022). "Furthermore, bone marrow plasma from HCL patients induces fibrosis of normal BM stroma in vitro and is neutralised by TGFB1 antibodies, highlighting the role of TGFB in the modulation of the stromal microenvironment of lymphoproliferative disorders." (PMID 35406544, 2022).
lysosomal storage disorders (1 paper, 2015). "Independent of TGFβ-1, E64d treatment caused a massive increase of enlarged lysosomes, a phenotype also found in lysosomal storage disorders." (PMID 25744631, 2015).
Menstrual disorder (1 paper, 2010). Category of disorders related to menstruation. "Furthermore, aberrant expression of TGFβ1 may contribute to menstrual disorders, such as heavy menstrual bleeding and painful menstruation, by modifying local haemostatic mechanisms." (PMID 20885978, 2010).
myosarcoma (1 paper, 2019). "As the interaction network of upregulated and downregulated miRNAs displays, we found that FOS, TGFB1, RB1 and ID2 are important genes controlling proliferation and apoptosis in myosarcoma." (PMID 30717351, 2019).
oligohydramnios (1 paper, 2024). A lower than normal quantity of amniotic fluid in the amniotic sac as compared to normal values. "Based on our results, we tested the capacity of the environmental variables (sex, family history, fetal presentation, and oligohydramnios) in conjunction with the variant rs1800470 in TGFB1, under the recessive model, to predict the occurrence of DDH." (PMID 38732313, 2024).
osteomalacia (1 paper, 2011). Disorder caused by an interruption of the mineralization of organic bone matrix leading to bone softening, bone pain, and weakness. "It is not understood, however, how the novel TGFβ1 defect, and perhaps RANKL change, causes this unique variant of CED with widespread skeletal disease and histopathological changes of osteomalacia." (PMID 21541994, 2011).
Pan (1 paper, 2022). "Results showed that higher TGFB1 expression levels correlated with lower progression-free survival in the TCGA PRAD dataset as well as a lower OS ratio in TCGA Pan-Cancer (PANCAN) dataset by Kaplan–Meier analysis, which was consistent with our previous findings." (PMID 35853880, 2022).
POEMS syndrome (1 paper, 2025). POEMS syndrome is a paraneoplastic syndrome characterized by polyradiculoneuropathy (P), organomegaly (O), endocrinopathy (E), clonal plasma cell disorder (M), and skin changes (S). "The pathogenesis mechanism of POEMS syndrome remains unclarified, but it may be linked to cytokine imbalances, including transforming growth factor β1 (TGFβ1), interleukin-6 (IL-6), and serum vascular endothelial growth factor (VEGF)." (PMID 40589976, 2025).
spina bifida (1 paper, 2023). A congenital neural tube defect in which vertebrae are not fully formed. "Patients suffering from SCI had significantly lower urinary levels of TGFβ-1 compared to spina bifida patients (10.8 pg/mL vs. 39 pg/mg; p = 0.04)." (PMID 36766573, 2023).
thymic adenocarcinoma (1 paper, 2017).
thymic benign tumors (1 paper, 2024). "Latency-associated peptide transforming growth factor beta 1 levels showed a causal relationship with thymic benign tumors (IWV, p = 0.042, OR = 0.327, 95% CI: 0.111–0.961)." (PMID 38828408, 2024).
vitreous hemorrhage (1 paper, 2020). Blood extravasation in the vitreous humor. "Furthermore, as regards the quantification of cytokines in sub-silicone oil fluid after vitrectomy, TGFβ1 levels were significantly higher (~3 fold) in patients with exacerbated PDR, compared to simple PDR (no re-proliferation of fibrotic membrane or vitreous hemorrhage)." (PMID 33334029, 2020).
tumor (15,509 papers, 1991 to 2026). "By contrast, PRKCSH was significantly positively correlated with TGFB1, a cytokine linked to M2-like, immunosuppressive programming in the tumor microenvironment." (PMID 41350724, 2025). "Tumour cells simulating the Kras mutation Tgfbr2 deletion in vitro were able to highly express and hyper‐secrete TGFβ1." (PMID 41431249, 2025). "The stick chart results of GC tumor associated immune cells and TGFβ1 correlation showed that NK cells (R=0.581), macrophages (R=0.490) and DCs (R=0.484) were highly correlated immune cells in GC." (PMID 39991579, 2025). "Clinical data demonstrate a strong association between TGF-β1 (transforming growth factor beta 1) and tumor pathogenesis, although the underlying mechanisms remain elusive." (PMID 40822022, 2025). "The association between PYGB and TGFB1, a pivotal cytokine in the regulation of immune responses and tumor progression, further emphasized the potential role of PYGB in fostering a tumor-supportive microenvironment." (PMID 40458414, 2025). "The pan cancer status and tumor associated immune cell correlation heatmap results of TGFβ1 in the TCGA database suggest that macrophages, DCs and NK cells are immune cells highly associated with TGFβ1 in GC." (PMID 39991579, 2025). "This TGF-β-driven immunosuppressive environment has been associated with resistance to PD-1/PD-L1 blockade, and tumours from resistant patients often exhibit elevated TGFβ1 transcription." (PMID 40806691, 2025). "Transcriptomic profiling further revealed elevated Cd8a and Ifng (markers of cytotoxic T cell infiltration/activity) alongside reduced Foxp3 (Tregs), Cd163 (M2-polarized tumor-associated macrophages), and Tgfb1 (immunosuppressive cytokine) in KO tumors." (PMID 41144132, 2025). "This drug can also inhibit the TGFβ1‐induced expression of pro‐fibrotic activation markers in adenocarcinoma tumor‐associated fibroblast parenchyma." (PMID 39083441, 2025). "We found that TBX3 is primarily expressed in malignant cells, where TBX3high tumor cells increase the secretion of TGFβ1, which promotes the infiltration of cancer-associated fibroblasts (CAFs), thereby forming an immunosuppressive microenvironment." (PMID 39897553, 2025). "Differential gene expression analysis using FindMarkers on tumor-associated macrophages revealed significant downregulation of M2 polarization markers (Arg1, Tgfb1) post-BBR treatment." (PMID 41585886, 2025). "We aimed to uncover the pro‐invasive role of PLVAP+ tip‐like ECs in the early progression of LUAD and to propose the TGFβ1‒PLVAP axis as a critical mechanism underlying early tumour–endothelium crosstalk." (PMID 41431249, 2025). "Ligands participating in these interactions are known immunosuppressive molecules (e.g., Tgfb1, Il1b), pro-angiogenic factors (e.g., Vegfa), or other genes associated with tumor progression (e.g., Fn1, Apoe, Apoc2)." (PMID 40216735, 2025). "HER2-targeted drug-resistant cancer cells correlate with increased levels of immunosuppressive molecules such as transforming growth factor-beta 1 (TGFβ1) and programmed cell death ligand 1 (PD-L1), causing resistance to the anti-tumor immune response." (PMID 40918454, 2025). "The activation of BFP expression in TGF SNIPR T cells generally scales with the production of TGFβ1 across tumour cell lines, as determined by enzyme-linked immunosorbent assay (ELISA)." (PMID 39542025, 2025). "Previous research has confirmed the interaction between tumor-enriched angiogenic ECs and Tumor-associated Macrophages (TAMs) through TGFB1 (angiogenic ECs) ⇔ TGFBR1 (Mye1, TAMs)." (PMID 39026350, 2024). "Expression of collagen genes (e.g., COL1A1 and COL1A2) is induced in tumor stromal cells such as cancer-associated fibroblasts (CAFs) and in tumor cells by transforming growth factor beta 1 (TGFβ1)-mediated phosphorylated SMAD3 (pSMAD3) signaling." (PMID 39574893, 2024).
tumor (continued). "Significant upregulation of expression is found in genes associated with tumor cell invasion such TGFβ1, ROAR, DAB2, BMP6, NOS2, PLXN2, and CADPS, whereas TCF4 was significantly downregulated in AHCY deficient cells." (PMID 38003292, 2023). "Higher immune inhibitor-associated genes like LAGs, VEGF, EDNRB, and TGFB1 were also upregulated, implying the critical role of lactate in a tumor immunosuppressive microenvironment." (PMID 37122693, 2023). "Among the genes encoding secreted proteins, the c-Kit+ ILC2_c1 population expressed XCL1 that involved in the recruitment of dendritic cells, and fibrosis-associated gene TGFB1 with either tumor-suppressing or tumor-promoting effects." (PMID 36960063, 2023). "TGFB1 is associated with tumor development, higher cell motility, cancer invasiveness, and metastasis in late stages, however." (PMID 37737288, 2023). "We also found that FJX1 expression is positively associated with TGFB1 and IL-10, which can induce macrophages to M2 polarization and regulate tumor immunology." (PMID 37324001, 2023). "We also showed that TGFB1 polarized M2-Tumor Associated Macrophages foster immune evasion and that TGFB1 expression correlates with reduced survival probability." (PMID 37460925, 2023). "Positive correlations were found between FJX1 expression and tumor-associated macrophages (TAMs) and with immune-related genes such as TGFB1 and IL-10 and immunosuppressive pathway-related genes such as TGFB1 and WNT1." (PMID 37324001, 2023). "Quantitative PCR (qPCR) of whole tumor lysate for transcript levels of the cytokines TGFβ (Tgfb1–2), IL10 (Il10), and IL35 (Ebi3 and Il12a), associated with suppressed antitumor immunity, showed reduced levels in Vegfr2Y1173F/+ tumors." (PMID 37651195, 2023). "Using PANC-1 cells as a model of SMAD4-intact PDAC and both BxPC-3 and AsPC-1 cells as a model of SMAD4-deficient PDAC, we next incubated tumor cells with 10ng/mL recombinant TGFβ1 for 24 hours and evaluated the expression of PD-L1 by western blot." (PMID 35155243, 2022). "Immune genes previously linked to a suppressive tumor microenvironment in WTs (TGFB1, IL10) are highly expressed in all EX2 tumors whilst activating genes (TNF, IL6) show a more restricted expression pattern." (PMID 36230794, 2022). "In the current SCLC cohort, downregulation of the inflammation marker (IGKV4-1), the tumor aggressivity associated marker (QSOX1), and the tumor suppressor marker (TGFβ1) were observed." (PMID 34996345, 2022). "Although the rate of tumor growth was significantly faster and greater in Piezo1-/- than in WT mice, IL-12 or anti-TGFβ1 antibody treatment significantly inhibited the tumor growth caused by Piezo1-/-." (PMID 35993548, 2022). "TGFβ1 promotes epithelial–mesenchymal transition and is associated with increased tumor cell motility and invasion." (PMID 35455650, 2022). "TGFβ1, a well-known secreted protein from the tumour, immune, and tumour-associated fibroblast cells, promotes tumour cell migration, invasion, and metastasis." (PMID 35406121, 2022). "We also assessed the expression levels of three proteins (E-Cadherin, N-Cadherin, TGFβ1) associated with tumor progression by IHC score." (PMID 35311069, 2022). "In our present study, CP-induced intracellular LLPS caused dramatically reduced TGFβ1 expression in tumor cells in vitro and in vivo." (PMID 36209170, 2022). "The interaction of the IL6 and TGFB1 signaling pathways plays an important role in SREs caused by tumor escape, bone colonization, and bone destruction." (PMID 35872837, 2022). "The expression of four CAF-specific markers correlated positively with that of CD68, CD163, MRC1, IL10, and TGFB1, which are markers that characterize tumor-associated macrophages (TAMs)." (PMID 33799788, 2021). "In normal and preneoplastic cells, TGFβ1 acts as a tumor suppressor associated with antiproliferative activity and apoptosis, but in advanced cancer stages, it acts as a tumor progression mediator." (PMID 34722128, 2021).